LEP (leptin)
Diseases named in the same sentence as LEP in open-access papers (continued):
Sharing a sentence is not in itself a finding about the gene and the disease.
Obesity (continued). "Leptin is an adipokine involved in the regulation of satiety and energy intake; levels of leptin in the plasma increase during the development of obesity and decline during weight loss." (PMID 24410812, 2014). "Our findings suggest that obesity-driven factors such as HGF/c-Met, insulin, and the leptin:adiponectin ratio may contribute to the onset of obesity-promoted BBCs, and that weight loss prior to tumor onset may prevent tumor progression." (PMID 25072025, 2014). "Adipocytokines such as TNFα, IL-6, adiponectin, leptin, visfatin, and resistin are cytokines secreted primarily by visceral adipose tissue and are thought to be involved in the positive correlation between obesity and the increased risk of gastric cancer." (PMID 24929539, 2014). "Obesity may increase risk of cancers because obese individuals have higher levels of leptin and lower levels of serum adiponectin, which is associated with chronic inflammation." (PMID 24884617, 2014). "Proposed explanations for this association include involvement of the obesity-related adipokines, adiponectin and leptin, although, among premenopausal women, specifically, the data supporting a breast cancer association for adiponectin (inverse) and leptin (positive) are inconsistent." (PMID 24790820, 2014). "Recently, it has been suggested that leptin may act as a cardiac hypertrophic factor linked to obesity and that concurrent elevated leptin levels are associated with cardiovascular risk, particularly in patients with HF." (PMID 24944619, 2014). "Given that obesity is associated with inflammation, which has been linked to both the risk for depression and the development of leptin resistance, the positive association observed in these Western studies may be ascribed to a higher BMI of the participants." (PMID 25079305, 2014). "Instead, these abnormalities may be attributable to leptin signaling in other cellular compartments such as NK cells or T cells, obesity and/or other features of the associated metabolic syndrome." (PMID 25232724, 2014). "We have previously demonstrated that chronic hyperleptinemia either induced in lean rats by exogenous administration of the hormone or “endogenous” hyperleptinemia associated with obesity induced by highly palatable diet impairs the acute vascular NO-mimetic effect of leptin." (PMID 24475175, 2014). "In the last years, clinical and preclinical studies have also found that leptin may represent a biological substrate underlying the pathogenesis of both obesity and depression." (PMID 25386150, 2014). "The relationship between leptin and catecholamine production may be of particular significance in the discussion of obesity as leptin has been implicated as a direct inducer of increased SNS outflow in obesity." (PMID 25018768, 2014). "Obesity is associated with leptin resistance; thus, the abnormal metabolism resulting from zinc deficiency may contribute to impaired wound repair." (PMID 24701367, 2014). "Obesity is associated with hyperleptinaemia and leptin resistance." (PMID 24736687, 2014). "In addition, animal study showed that GNAS knock-out mice with an insertion mutation on maternal allele develops obesity with increased serum leptin levels and lipid accumulation." (PMID 25269528, 2014). "Therefore, the mutations in LEP can possibly damage the function of leptin and disturb the metabolic balance in humans, which is directly responsible for severe obesity and other metabolic disorders." (PMID 24707501, 2014). "Several mutations in LEP have been confirmed to be associated with monogenic obesity." (PMID 24707501, 2014). "However, the OHS mouse model of obesity is caused by a global leptin deficiency that removes inhibition on hypothalamic centers controlling satiety." (PMID 24771695, 2014). "However, the genetic changes that exist in these animals (usually mutations in leptin or its receptor) that result in hyperphagia and obesity are rare in humans, and the obese phenotype in these mice is severe." (PMID 24732966, 2014).
Obesity (continued). "High fat diet-induced obesity is associated with adipocyte hypertrophy and leptin resistance." (PMID 24609135, 2014). "We speculated that the mutation H118L in LEP might be associated with severe obesity in Chinese subjects." (PMID 24707501, 2014). "Instead, leptin signaling in other cells within or outside the lung including T cells and NK cells or obesity and its associated metabolic consequences may be important for viral clearance following influenza A infection." (PMID 25232724, 2014). "Obesity is a risk factor for osteoarthritis and the growth in fat mass is directly proportional to exaggerated consumption of nutrients, especially saturated fatty acids, responsible for low grade inflammation and central resistance to insulin and to leptin." (PMID 25184806, 2014). "Leptin and adiponectin are important enzymes that are associated with obesity." (PMID 24936481, 2014). "By the fact that leptin levels are enhanced in obese subjects, this hormone can be considered as a relevant candidate acting on central nervous system and contributing to the cardiovascular changes associated with obesity." (PMID 25009507, 2014). "Plasma leptin levels are markedly increased in obesity and associated metabolic syndrome." (PMID 24499246, 2014). "Higher plasma leptin levels are associated with obesity, insulin resistance, and MS." (PMID 25653879, 2014). "Additionally, leptin-deficient ob-/- mice, despite their genetic obesity, have many features similar to those seen in malnutrition, including decreased body temperature, infertility, and low metabolic rate." (PMID 25157251, 2014). "Leptin is necessary for the development and progression of OA associated with obesity." (PMID 24741591, 2014). "On the other hand, leptin, was only associated with weight status and thus remains a potential mediator of the association found between overweight/obesity and allergy incidence, although only in girls, since boys with allergy symptoms maintained normal leptin levels." (PMID 24405509, 2014). "Increased leptin concentration in MS may represent a form of leptin resistance, as in obese subjects; obesity is one of the risk factors for MS." (PMID 24444121, 2014). "Hyperinsulinaemia and hyperleptinaemia are associated with increased seminal insulin and leptin concentrations, which may negatively impact male reproductive function in obesity." (PMID 24885899, 2014). "So far, the molecular mechanisms underlying the abnormal expression of leptin in obesity remain unclear." (PMID 24923522, 2014). "In order to determine whether these results would also apply to a genetic model of obesity, we used the leptin-deficient ob/ob mouse in a subsequent set of experiments." (PMID 25216251, 2014). "Notably, obesity in humans is thought to be caused by an impaired transport of leptin across the blood–brain barrier (BBB), making leptin-targeted drugs potentially inappropriate for use in obese individuals." (PMID 25407801, 2014). "Excessive body fat accumulation and obesity are associated with increased levels of leptin." (PMID 24868483, 2014). "In fact, while the discovery of leptin can be thought of as part of the process of investigation into the pathological causes of obesity, adiponectin was instead isolated via experiments whose purpose can best be described as aimed at improving our understanding of basic adipocyte biology." (PMID 25177314, 2014). "In obese individuals, low ZAG gene expression is associated with low serum adiponectin and high plasma leptin levels, and may play an important role in the pathogenesis of obesity." (PMID 24555483, 2014). "Thus, leptin is a significant indicator of metabolic syndrome, and the same relationship between leptin and obesity creates a high risk factor for the development of metabolic syndrome." (PMID 24879081, 2014).
Obesity (continued). "Prolonged feeding with a high-fat diet (HFD) or the disruption of leptin signalling in leptin-deficient (ob/ob) and leptin receptor-deficient (db/db) hyperphagic mice results in hepatic steatosis accompanied by obesity, IR, changes in lipid and glucose homoeostasis and oxidative stress." (PMID 24913135, 2014). "Herein we extend our previous work on the association of obesity and adenoma by analyzing whether adiponectin and leptin mediate the relationship between adiposity and colon adenoma in a sample of Caucasians and African Americans." (PMID 25197277, 2014). "As obesity is considered to cause several diseases, based on the results of our research, more studies are needed to determine the impact and the mechanism of 5HT on leptin and adiponectin." (PMID 24886049, 2014). "The association between GBM and obesity may be explained by the important role of leptin in both of these two diseases." (PMID 25041817, 2014). "This resistance could be inherited or secondary to obesity, associated with a less efficient transport of leptin via the BBB or abnormalities in leptin signaling." (PMID 24795698, 2014). "Genetic factors such as leptin gene polymorphism, environmental and dietary factors such as Ca2+ and vitamin D deficiency, and comorbidities such as obesity and diabetes may increase the susceptibility of pregnant women to develop preeclampsia." (PMID 24195082, 2013). "Consequently, Ugcgf/f//CamKCreERT2 mice with deficient leptin-induced hypothalamic neuronal responsiveness develop progressive obesity." (PMID 23554574, 2013). "However, ob/ob mice do not exhibit steatohepatitis, including inflammation and fibrosis, because of their leptin deficiency despite significant obesity." (PMID 24192824, 2013). "Since leptin inhibits food intake through its action, it is believed that reduced leptin levels might be the cause of obesity and indeed, several obese individuals were identified with low leptin levels." (PMID 24051404, 2013). "Further implications of our finding of dendritic LepRb localization include the possibility that leptin-resistant obesity may be caused, at least in part, by altered LepRb expression or signaling in this neuronal compartment." (PMID 24204898, 2013). "Leptin deficiency not only leads to obesity, but also to diabetes and to reproductive dysfunction." (PMID 23634778, 2013). "The objective of the current study was to determine the underlying potential contribution of alterations in hepatic mitochondrial function and content as well as de novo lipogenesis to NAFLD development in the commonly studied model of obesity, the leptin-deficient Ob/Ob mouse." (PMID 23401753, 2013). "Null mutation of the leptin gene (Ob) produced significant hyperphagia and severe obesity." (PMID 23543912, 2013). "Their study found that obesity in ob/ob mice was caused by leptin deficiency and that hyperglycemia might confound the process of hearing degeneration." (PMID 23637762, 2013). "The hyperinsulinemia in ob/ob mice might be caused by the impairment of leptin signaling in pancreatic β-cells and contributes to obesity and insulin resistance." (PMID 23579596, 2013). "Moreover, we determined the importance of leptin-mediated STAT3 activation for the development of cardiac hypertrophy in obesity by analyzing mice with targeted mutation of the STAT3 binding site within LepR." (PMID 23841921, 2013). "In addition, recent findings have implicated leptin resistance and defective leptin receptor b trafficking in the hypothalamus to obesity in Bbs4−/− mice." (PMID 23554981, 2013). "Leptin has been extensively studied as a potential mediator of obesity-associated cancer." (PMID 23819063, 2013). "Leptin is positively associated with diabetes, obesity, and metabolic syndrome, but by its proangiogenic, antiapoptotic properties may exert a mitogenic influence on breast and pancreatic cancer cells." (PMID 23476808, 2013).
Obesity (continued). "Leptin was one of the earliest hormones involved in energy balance to be identified and found to be the responsible factor deficient in the severely obese ObOb mouse model of obesity." (PMID 23766565, 2013). "In marked contrast to these studies that were mainly based on association between leptin and indicators of disease in obesity, surprisingly little is known regarding the leptin receptor on neutrophils and the functional responsiveness of these cells to this adipokine." (PMID 24066032, 2013). "In turn, intake of carbohydrate supplements in rats during gestation appears to program insulin and leptin resistance in adult offspring and may predispose to the development of obesity under palatable energy dense diets." (PMID 24062695, 2013). "Furthermore, mice lacking AC3, which is a downstream regulator of olfactory receptors, exhibit obesity that is apparently caused by low locomotor activity, hyperphagia, and leptin insensitivity." (PMID 23555558, 2013). "The adipocytokine leptin may link obesity with cardiac hypertrophy, an important risk factor for the development of heart failure." (PMID 23841921, 2013). "Recently, the therapeutic effects of central leptin gene therapy have been reported in insulin-deficient diabetes in obesity animal models such as ob/ob mise, diet-induced obese mice, and insulin-deficient type 1 diabetes mice, and also in patients with inactivating mutations in the leptin gene." (PMID 23579596, 2013). "Obesity could increase the risk of cholangiocarcinoma by affecting the levels of leptin, adiponectin, and pro-inflammatory cytokines." (PMID 23894567, 2013). "One implication is that leptin exposure during specific periods in development may influence future risk of obesity." (PMID 23825665, 2013). "However, NPY deficiency in ob/ob (leptin deficient) mice was found to attenuate the obesity phenotype by reducing food intake and increasing energy expenditure." (PMID 23092275, 2013). "A variant in the promoter region (−2548A/G) of the leptin gene has been associated with obesity." (PMID 24772381, 2013). "Obesity is associated with a state of chronic or low grade systemic inflammation which increases production of obesity-related inflammatory cytokines, such as IL-1β, IL-6, TNFα, leptin and decrease anti-inflammatory cytokine levels, such as adiponectin." (PMID 24143244, 2013). "Obesity is linked with significant increase in serum leptin and decrease in adiponectin." (PMID 24302863, 2013). "Fat composition data could be valuable for the adjustment of the association of rs8061518 with leptin in order to clarify the role of the genetic variant on obesity." (PMID 24289790, 2013). "The resulting state of leptin central resistance, characterized by the failure of high levels of leptin to suppress food intake and decrease adiposity, is a hypothesized shared biological mechanism underlying obesity and depression." (PMID 23672628, 2013). "This phenomenon known as leptin resistance is characteristic of obesity and may explain how the risk of mood disorders is elevated in obese states associated with high circulating leptin levels." (PMID 24109426, 2013). "Increased levels of leptin in obesity could be linked to chronic hyperinsulinemia and increased cortisol turnover." (PMID 24202338, 2013). "Association of rs9939609 variant with higher FBG, plasma insulin, and leptin levels indicates that this polymorphism may disturb the metabolism in adult females and predispose them to obesity and type 2 diabetes." (PMID 24102053, 2013). "This epigenetic inhibition of the LEP gene by COS in differentiating adipocytes could have implications for leptin regulation and for associated metabolic syndrome diseases such as obesity and type-2-diabetes." (PMID 23544120, 2013). "Therefore, the close correlation between hyperleptinemia and body weight has resulted in recognition of leptin resistance as a cause of obesity." (PMID 23864899, 2013).
Obesity (continued). "The impaired leptin activity in the hippocampus is a clue to obesity-associated depression." (PMID 23579596, 2013). "We propose that loss of the MAGEL2 gene in people with Prader-Willi Syndrome may cause deficient leptin sensing, leading to the increased appetite and obesity that are hallmarks of this genetic condition." (PMID 23341784, 2013). "The therapeutic effects of central leptin gene therapy have been reported in insulin-deficient diabetes and in obesity animal models, such as ob/ob, diet-induced obese mice, insulin-deficient type 1 diabetes mice, and insulin-dependent diabetes animals (Akita mice)." (PMID 23579596, 2013). "Thus leptin deficient Lepob/Lepob and leptin receptor deficient Leprdb/Leprdb mice display marked hyperphagia, obesity, and insulin resistance." (PMID 23781214, 2013). "Moreover, an OX1R-selective antagonist-reduced food intake and ameliorated obesity in leptin-deficient ob/ob mice, suggesting that leptin deficiency at least partly activates the orexin pathway to increase food intake." (PMID 23616752, 2013). "Additionally, we observed for the first time, the association of rs8061518, localized in the third intron of the gene, with a reduced risk of obesity and low plasma leptin concentrations." (PMID 24289790, 2013). "Obesity is also recognized as the risk factor for stroke, because obesity is associated with hypertension and inflammation via secretion of adipokines, such as adiponectin, leptin, resistin, adipsin, plasminogen activator inhibitor-1, and inflammatory cytokines." (PMID 23431245, 2013). "Moreover, increased leptin levels are associated with the inflammatory process and potentially the entire increased morbidity of obesity." (PMID 23662101, 2013). "Similarly, rats born to obese dams have elevated plasma leptin in the first 3 weeks of life, and this is associated with resistance to the anorexigenic effects of leptin, hyperphagia, and obesity long-term." (PMID 23785312, 2013). "In a rodent study to establish whether neonatal (postnatal day 3–13) leptin treatment can alleviate postnatal obesity and the associated metabolic sequelae that occur in the offspring of undernourished dams, leptin treatment reversed the programmed phenotype." (PMID 23476780, 2013). "Defects in leptin signaling lead to leptin resistance, which is a primary risk factor for obesity." (PMID 23579596, 2013). "Interestingly, higher levels of serum leptin appear to protect against cognitive decline in elderly individuals, suggesting leptin resistance as a causal pathway from obesity to cognitive impairment." (PMID 23570390, 2013). "A critical role for endogenous BDNF in the regulation of feeding behavior was demonstrated in mice with reduced BDNF levels, such as heterozygous BDNF (Bdnf+/−) mice, which had increased risk of obesity resulting from increased food intake, concomitant with elevated serum leptin and insulin levels." (PMID 23519010, 2013). "Hence, the Iberian swine, having in mind is unique characteristic of leptin resistance, is specially useful as a robust, amenable and reliable translational model for studies on obesity, metabolic syndrome and nutrition-associated diseases in humans." (PMID 23935823, 2013). "Here, we exposed wild type (LETO) females to an early obesogenic environment and genetically obese OLETF females to a lean postnatal environment, to assess long term alterations in leptin sensitivity, predisposition to diet induced obesity and adult female health." (PMID 23544111, 2013). "Lower vitamin E concentrations have also been associated with obesity in some populations and, as with vitamin C, this association could be due to its role in leptin metabolism." (PMID 24335710, 2013). "One mechanism underlying this relationship may involve the growth-promoting effects of the circulation hormones associated with obesity and insulin resistance, such as leptin." (PMID 23593308, 2013).